TSLP (thymic stromal lymphopoietin)
Diseases named in the same sentence as TSLP in open-access papers (continued):
Sharing a sentence is not in itself a finding about the gene and the disease.
asthma (continued). "Several genes within the cytokine gene cluster on chromosome 5, specifically IL3, IL4, CSF2, TSLP, IL5, RAD50, and IL13, are recognized as potential asthma susceptibility genes due to their roles in inflammatory regulation among sensitized asthma patients." (PMID 41001556, 2025). "In short, basophils play a crucial role in initiating asthma during the inflammatory state of AD, and TSLP has the potential to drive this process." (PMID 40443683, 2025). "TLR2 promotes Th2 cell polarization in asthma by thymic stromal lymphopoietin (TSLP)-mediated NF-κB and JNK signaling pathways activation in the airway epithelial cells." (PMID 41293166, 2025). "In typical Th2‐high phenotype asthma, airway epithelium interacts with environmental factors to induce innate and adaptive immune and inflammatory responses, releasing TSLP, IL‐33, and IL‐25." (PMID 39800672, 2025). "Following that finding, TSLP expression was found in the airways of patients with asthma and in the nasal lavages of individuals with allergic rhinitis." (PMID 40873585, 2025). "Medical treatment focused on Type 2 inflammation, such as IgE, Th2 cytokines, and group 2 innate lymphoid cells (ILC2s) due to TSLP, is probably insufficient to maintain good long-term management (complete remission) for severe asthma." (PMID 40001485, 2025). "Tezepelumab is an anti-TSLP monoclonal antibody licenced for the treatment of severe refractory asthma and has been shown to reduce exacerbations and improve lung function in this cohort." (PMID 39721985, 2025). "By reducing and normalizing key inflammatory mediators such as CCL26 and TSLP, while preserving essential antiviral defense mechanisms, IL-4Rα blockade offers a balanced approach to managing asthma symptoms and preventing exacerbations." (PMID 40370530, 2025). "A particularly interesting finding in our study was the clear differences in TSLP levels between asthma-derived BECs and healthy BECs under T2-driven inflammatory conditions." (PMID 40370530, 2025). "TSLP, IL-25, and IL-33 are key players in type 2 inflammatory responses associated with allergic rhinitis (AR), CRS, and asthma." (PMID 39940994, 2025). "TSLP's demonstrated necessity for HD Tm immunity, and the recent emergence of anti‐TSLP treatments for human asthma, make further investigation of the alarmin's presently mysterious mechanism of action particularly valuable." (PMID 40944312, 2025). "When analyzing circulating levels of Th2 biomarkers across asthma groups, serum TSLP was the only biomarker that exhibited significant differences, with elevated levels in acute exacerbation and persistent asthma compared to remission." (PMID 40503233, 2025). "During the course of both diseases, IL-25, IL-33, and TSLP cytokines are notably increased, which are all substantial in provoking a pathological immunologic response, proven in a mouse asthma model, and TSLP alone in a mouse AD model." (PMID 40149608, 2025). "Tezepelumab, an anti-TSLP antibody, significantly reduced exacerbation and airway inflammation in severe asthma, confirming the importance of upstream epithelial alarmin signaling." (PMID 41294800, 2025). "Tezepelumab, a monoclonal antibody against TSLP and TSLP-blocking, was effective for asthma exacerbations and improved asthma control, with a suggestion of a pathway towards remission in a subgroup of patients." (PMID 40283665, 2025). "Airway expression levels of TSLP are related to both asthma severity and the extent of bronchial obstruction occurring in asthmatic patients." (PMID 41321706, 2025). "Tezepelumab, which targets TSLP, is indicated for add-on maintenance therapy for inadequately controlled severe asthma and enhances AIT efficacy in AR triggered by cat allergy." (PMID 40234356, 2025). "Thymic stromal lymphopoietin (TSLP) released from injured airway epithelial cells contributes to steroid resistance in severe asthma." (PMID 41211661, 2025).
asthma (continued). "Spearman’s correlation coefficients between serum TSLP level and other clinical characteristics in children with Th2 high asthma." (PMID 40503233, 2025). "Given that males with asthma were found to have more type 2 cells (ILC2s) but less alarmin cytokines (TSLP) and type 2 cytokines (IL‐13) compared to females, we explored the role of miRNAs as an additional modulator of the immune response." (PMID 40022441, 2025). "In one included study, the distribution of serum TSLP concentrations in patients with asthma (n = 182) and healthy controls (n = 47) demonstrated a non-normal, right-skewed pattern in both groups." (PMID 41357156, 2025). "Tezepelumab, a human monoclonal antibody that targets TSLP to block its interaction with the heterodimeric receptor, is the leading antialarmin in advanced clinical development aimed at treating asthma." (PMID 39962262, 2025). "In asthma, epithelial exposure to allergens (dust mite proteases and pollen) induces IL‐33/TSLP, driving ILC2‐mediated IL‐13 production that increases airway epithelial permeability and goblet cell metaplasia." (PMID 40679787, 2025). "Our findings reveal that serum TSLP levels significantly differ across asthma stages, with the highest levels in acute exacerbation and persistent asthma, and the lowest in clinical remission." (PMID 40503233, 2025). "Solrikitug is a humanized anti-TSLP monoclonal antibody in phase 2 development for asthma (NCT06496607), COPD (NCT06496620), and EoE (NCT06598462)." (PMID 41409758, 2025). "GB-0895 is an anti-TSLP monoclonal antibody engineered to have an extended half-life and is currently in phase 1 development in patients with asthma and COPD (NCT07116889)." (PMID 41409758, 2025). "Tezepelumab is a monoclonal antibody that inhibits the alarmin thymic stromal lymphopoietin (TSLP) and was recently approved for the treatment of severe asthma." (PMID 41473842, 2025). "Increased concentration and expression of TSLP in blood and airway specimens in asthmatic patients compared with healthy controls highlight its potential utility as a biomarker for asthma management." (PMID 41357156, 2025). "Emerging evidence has identified elevated TSLP levels in asthma and chronic obstructive pulmonary disease (COPD), where it exacerbates inflammation and steroid insensitivity through the activation of Th2 cell responses and eosinophilic infiltration." (PMID 40861437, 2025). "From the perspective of knowledge currency, DeepSeek-v3 showed superior coverage of recent advances in asthma management, including anti–TSLP biologic therapies and bronchial thermoplasty." (PMID 40802989, 2025). "Air pollutants contribute by activating type 2 pathways, promoting epithelial cytokine release (IL‐33 and TSLP), oxidative stress, and pro‐inflammatory mediators (IL‐6, IL‐8, and IL‐1β) relevant to asthma." (PMID 40679787, 2025). "TSLP, which targets immune cells to release pro-inflammatory cytokines, plays an important role in the pathogenesis of asthma." (PMID 40520782, 2025). "With the advancements in TSLP-targeted biologics, it has been widely recognized as a therapeutic target in severe asthma due to its role in driving Th2-mediated inflammation and airway remodeling." (PMID 40503233, 2025). "Its critical role in asthma has been highlighted through clinical studies evaluating the effects of blocking TSLP signaling on inflammation and disease progression." (PMID 40149651, 2025). "Further relevant data regarding the impact of TSLP blockade in CRSwNP come from the phase 3 NAVIGATOR study of tezepelumab in patients with severe uncontrolled asthma." (PMID 40919679, 2025). "Thymic stromal lymphopoietin (TSLP) is an epithelium-derived cytokine with a key role in the initiation and amplification of asthma inflammation." (PMID 40283665, 2025).
asthma (continued). "In the current study, we found significant differences between males and females with asthma in the number of eosinophils and ILC2s, levels of IL‐13, TSLP, soluble ST2 (sST2) and ST2L expression on ILC2s in the airways." (PMID 40022441, 2025). "Tezepelumab, a monoclonal antibody targeting thymic stromal lymphopoietin, has demonstrated efficacy for severe asthma in clinical trials, but real-world evidence remains limited." (PMID 40901376, 2025). "TSLP is a cytokine derived from epithelial cells that plays a pivotal role in the development of asthma and various allergic conditions." (PMID 40636260, 2025). "Lunsekimig (anti-IL-13/anti-TSLP) is a nanobody that blocks both IL-13 and TSLP and is currently included in a phase II clinical trial for moderate-to-severe asthma (AIRCULES)." (PMID 40364184, 2025). "Based on meta-analysis, blood TSLP concentration was significantly higher in patients with asthma than in controls (SMD = 3.66, 95% CI 1.63–5.69, I2 = 98.26%)." (PMID 41357156, 2025). "Studies have demonstrated that TSLP mRNA expression is elevated in nasal polyps and epithelial cells from individuals with asthma, atopic dermatitis, COPD (chronic obstructive pulmonary disease)." (PMID 39940994, 2025). "Blocking TSLP disrupts this cascade, a principle validated by anti-TSLP therapy in asthma clinical trials." (PMID 41471371, 2025). "This action helps to prevent TSLP from binding to its receptor, thereby reducing the immune response triggered by TSLP in various types of asthma." (PMID 40303400, 2025). "Although no clinical trials have yet been conducted on TSLP inhibitors for BP treatment, Tezepelumab—a human monoclonal antibody targeting TSLP—is currently in trials for asthma and AD." (PMID 40264772, 2025). "Mechanistic clinical trials have helped to understand mechanisms of TSLP in the pathogenesis of asthma." (PMID 39457624, 2024). "In patients with severe asthma, the number of peripheral eosinophils producing EETs is elevated, and these cells stimulate lung epithelial cells to generate IL-33 and TSLP." (PMID 39060923, 2024). "Targeting TSLP and its signaling pathways is increasingly recognized as an effective strategy for asthma treatment." (PMID 38536788, 2024). "Biologics drugs neutralizing excess TSLP activity represented by tezepelumab have been approved for severe asthma and are being evaluated for the treatments of other TSLP-mediated diseases." (PMID 39726595, 2024). "Most prominently, a phase 3 clinical trial testing tezepelumab, a human monoclonal blocking TSLP, reported improved frequency of asthma exacerbations, lung function, asthma control, and quality of life." (PMID 39200943, 2024). "Studies investigating the role of TSLP in asthma demonstrate a correlation, indicating elevated serum levels of TSLP in asthmatic patients compared to healthy individuals." (PMID 38731070, 2024). "Genome-wide association studies and successful phase 2/phase 3 clinical trials support the critical role of IL-33 and TSLP in human asthma." (PMID 38597952, 2024). "The remarkable advantage of this antibody lies in its ability to effectively block the interaction between TSLP and downstream proteins, offering a promising therapeutic approach for TSLP-related diseases, particularly asthma." (PMID 38536788, 2024). "Once released from the epithelium, TSLP binds to its receptors on a broad range of immune cells and activates multiple effector cells involved in the pathogenesis of asthma, most notably dendritic cells (DCs)." (PMID 38672419, 2024). "Targeted antibody drugs against TSLP and its signaling pathway are considered effective strategies for asthma treatment." (PMID 38536788, 2024). "Upstream epithelial cytokines, collectively termed alarmins (such as thymic stromal lymphopoietin (TSLP) and IL-33), have been established as key drivers of asthma pathobiology from the top of the immunologic cascade." (PMID 39694589, 2024).
asthma (continued). "Similar to our basal cell line data, pBECs from both control subjects and patients with severe asthma (n = 5) had a significant increase in TSLP mRNA induction upon tunicamycin challenge." (PMID 38469627, 2024). "Through this research, we have obtained an antibody with high affinity for TSLP, providing a new avenue for treating asthma and other TSLP-related diseases." (PMID 38536788, 2024). "The development of ecleralimab (CSJ117) highlights the ongoing innovation in targeting TSLP to manage asthma." (PMID 39457624, 2024). "In the phase 3 trial, Tezepelumab, a monoclonal antibody targeting TSLP, significantly minimized exacerbation of symptoms across all seasons in patients with uncontrolled asthma, including those with seasonal and perennial allergies." (PMID 38541674, 2024). "At present, a mAb directed against TSLP (tezepelumab), has been approved for treating severe asthma in step 5 of the GINA guidelines." (PMID 39439788, 2024). "Targeting thymic stromal lymphopoietin and its signaling pathways with specific antibody drugs is widely recognized as an effective strategy for treating asthma." (PMID 38536788, 2024). "The aim of this study was to analyze the involvement of IL-33 and TSLP in pediatric asthma, exploring their role in children with mild asthma." (PMID 38731070, 2024). "There are several biological drugs currently available to treat severe asthma: anti-IL-5 (mepolizumab, reslizumab, benralizumab), anti-IgE (omalizumab), anti-IL-4/IL-13 (dupilumab), and anti-TSLP (tezepelumab) agents." (PMID 39685611, 2024). "The higher serum concentration of TSLP correlate with the severity of asthma, declining pulmonary functions and reduce corticosteroid sensitivity." (PMID 39118763, 2024). "On a clinical ground tezepelumab, selectively binding TSLP, a major epithelial cytokine, has demonstrated to be effective in asthma patients regardless their specific phenotype." (PMID 39385131, 2024). "Among these, TSLP, IL-25, and IL-33 play pivotal roles as upstream regulators, initiating and amplifying inflammatory pathways that drive asthma symptoms, making them critical targets for therapeutic interventions." (PMID 39457624, 2024). "Here, we found that during asthma, the epithelial alarmin TSLP induces the expression of CUL5, which acts as a master regulator of IFN-β production in AMs, thereby controlling neutrophil accumulation and its associated effects in the airways." (PMID 38177117, 2024). "TSLP plays a key role in the initiation and persistence of asthma, making it a significant therapeutic target." (PMID 39457624, 2024). "Tezepelumab, a humanized monoclonal antibody targeting thymic stromal lymphopoietin (TSLP), has demonstrated promise in reducing eosinophilic inflammation, airway hyperresponsiveness, and asthma exacerbations." (PMID 39598421, 2024). "Tezepelumab, a monoclonal antibody targeting TSLP, has been studied in clinical trials of over 1500 patients and has been approved for clinical use in asthma in patients over 12 years of age." (PMID 38672419, 2024). "There are currently several classes of biologics approved for severe asthma including anti-immunoglobulin E, anti-interleukin-5/interleukin 5R, anti-interleukin 4/interleukin 13R, and anti-thymic stromal lymphopoietin." (PMID 38291489, 2024). "Airway levels of both TSLP and IL-33 are elevated in patients with asthma compared with healthy individuals and correlate with disease severity." (PMID 38609094, 2024). "Damaged epithelial cells release several cytokines, termed alarmins [i.e., thymic stromal lymphopoietin (TSLP), IL-33, and IL-25], which drive asthma immunology." (PMID 38612858, 2024). "We previously highlighted the central role of TSLP in mediating mucosal inflammatory diseases of which ocular surface allergy and asthma are prime examples." (PMID 38541674, 2024). "Tezepelumab, a human monoclonal IgG2λ antibody that blocks TSLP, is the primary drug targeting TSLP and is mainly used for the treatment of asthma." (PMID 39677857, 2024).
asthma (continued). "We used Tezepelumab, which is an FDA-approved anti-TSLP mAb under the brand name of Tezspire for the treatment of asthma as a control." (PMID 38566968, 2024). "The release of TSLP leads to the development of inflammation which, when unchecked, can result in asthma exacerbations." (PMID 38672419, 2024). "In nasal brushings, GINA 5 asthma patients expressed significantly higher levels of both TSLP and IL-25 when compared to all other asthma patients combined (GINA 1–4, p < 0.001 and p < 0.002, respectively, after adjusting for age and sex)." (PMID 38999286, 2024). "With the arrival of anti-TSLP therapy in severe asthma, we will continue to discover the clinical relevance of modulating epithelial responses to inhaled triggers and infectious insults." (PMID 38672419, 2024). "The absolute concentrations of periostin and TSLP were higher in patients with asthma compared to patients with COPD and controls." (PMID 38892164, 2024). "Results from emerging clinical trials of anti-TSLP agents have already confirmed the efficacy of treatment in many inflammatory conditions, such as asthma." (PMID 38911857, 2024). "They empress pattern recognition receptors that detect the stimuli and secrete “alarmin cytokines” including IL-25, IL-33 and TSLP, which contributes to the pathogenesis of asthma." (PMID 38641850, 2024). "In TSLP/OVA induced asthma model, the intranasal administration of TSLP/OVA significantly induced the elevation of serum IgE level and key inflammatory cytokines CCL17 and IL-13 levels in the lung which contributed to the disease establishment and progression." (PMID 39726595, 2024). "Thymic stromal lymphopoietin (TSLP), mainly expressed by epithelial cells, plays a central role in asthma." (PMID 38612858, 2024). "Tezspire (tezepelumab) is currently the only approved thymic stromal lymphopoietin (TSLP) inhibitor for asthma and is also under evaluation as a potential candidate for food allergies." (PMID 39493746, 2024). "Patients with asthma, especially those with severe asthma, have been found to exhibit increased levels of TSLP and T2 cytokines in the airways and ILC2s in their peripheral blood and BALF compared to healthy individuals." (PMID 39685875, 2024). "While this is the first report demonstrating increased upper airway expression of TSLP in severe asthma patients, there are important study limitations." (PMID 38999286, 2024). "Epithelium-derived cytokines or alarmins, such as interleukin-33 (IL-33) and thymic stromal lymphopoietin (TSLP), are major players in type 2 immunity and asthma." (PMID 38597952, 2024). "In the last two decades, the cytokine thymic stromal lymphopoietin (TSLP) has emerged as an important factor in the pathogenesis of asthma." (PMID 39118763, 2024). "Thymic stromal lymphopoietin is a key cytokine involved in the pathogenesis of asthma and other allergic diseases." (PMID 38536788, 2024). "TSLP, IL-25, and IL-33 are regarded as primary molecules involved in type 2 inflammatory response and have a crucial role in the pathogenesis of asthma." (PMID 39060923, 2024). "Sputum IL-25 is greater in obese as compared to lean asthmatics while BAL IL-33 and TSLP are greater in obese as compared to lean mice with experimental asthma." (PMID 38878250, 2024). "For instance, recently, Tezepelumab, a human IgG2 monoclonal antibody that inhibits the binding of TSLP to its receptor, has been undergoing clinical trials for asthma treatment." (PMID 38911857, 2024). "Tezepelumab is a human monoclonal antibody that inhibits thymic stromal lymphopoietin (TLSP) that has proven efficacy in several phase 3 studies for the treatment of asthma." (PMID 38992639, 2024). "Variants of several genes are associated with the risk of both IgE-mediated food allergy and asthma, including C11orf30, STAT6, and thymic stromal lymphopoietin (TSLP)." (PMID 39594870, 2024).